HIGD1C (HIG1 hypoxia inducible domain family member 1C)
Synonyms: Gm921
Tractability: Antibody: UniProt predicts a signal peptide or a membrane-spanning region.
Gene: Protein-coding gene on chromosome 12 (50,952,538 to 50,970,607, forward strand). Ensembl gene ENSG00000214511.
Subcellular location: Membrane
Pathways (Reactome):
Cellular responses to stimuli: Cytoprotection by HMOX1
Metabolism: Respiratory electron transport
Gene Ontology:
Molecular function: protein binding
Biological process: mitochondrial respirasome assembly
Cellular component: mitochondrion; membrane
Genetic constraint (gnomAD): Loss-of-function variants: 5 observed, 4.92 expected, observed/expected ratio (o/e) 1.02, 90% interval 0.52 to 1.82. That is too few expected variants to judge how well the gene tolerates losing a copy. Missense variants: 52 observed, 55.59 expected, observed/expected ratio (o/e) 0.94, 90% interval 0.75 to 1.18. Synonymous variants: 13 observed, 16.94 expected, observed/expected ratio (o/e) 0.77, 90% interval 0.5 to 1.22.
Homologues: Orthologues: chimpanzee HIGD1C (99% identical), dog HIGD1C (93% identical), macaque HIGD1C (93% identical), pig HIGD1C (90% identical), guinea pig HIGD1C (89% identical), rabbit HIGD1C (89% identical), mouse Higd1c (81% identical), rat Higd1c (81% identical), zebrafish higd1a (54% identical), Drosophila melanogaster CG11825 (40% identical), Drosophila melanogaster CG9921 (27% identical), Caenorhabditis elegans T20D3.6 (18% identical). Paralogues in human: HIGD1A (58% identical), HIGD1B (44% identical), HIGD2B (29% identical), HIGD2A (28% identical).
Diseases named in the same sentence as HIGD1C in open-access papers:
HIGD1C is named in the same sentence as 3 diseases in open-access papers, as found by Europe PMC text mining. Sharing a sentence is not in itself a finding about the gene and the disease. The quoted sentences say what the papers report.
depression (1 paper, 2021). "For the depression PHQ score, two significant gene × blood VD interactions were identified at SLC11A2 and HIGD1C (rs117102029, p = 4.02 × 10−8)." (PMID 34684344, 2021). "In addition, we identified multiple candidate genes which interacted with vitamin D for the depression PHQ score, such as SLC11A2 and HIGD1C." (PMID 34684344, 2021).
psychiatric disorder (1 paper, 2021). A disorder characterized by behavioral and/or psychological abnormalities, often accompanied by physical symptoms. "Nevertheless, no studies have shown a direct link between VD and the effects of SLC11A2 and HIGD1C genes on the nervous system and psychiatric disorders." (PMID 34684344, 2021).
HIGD1C also shares sentences with these, for which no sentence is quoted: infection (1 paper).